KRAS (KRas proto-oncogene, GTPase)
Diseases named in the same sentence as KRAS in open-access papers (continued):
Sharing a sentence is not in itself a finding about the gene and the disease.
pancreatic cancer (continued). "It is a regulator of proteins involved in RAS signaling pathways and is highly expressed in several cancers with KRAS mutation including lung, colorectal, and pancreatic cancers." (PMID 35057033, 2022). "An expanding body of knowledge underlying the molecular pathogenesis of the disease has revealed that genetic alterations, such as KRAS mutations, and especially epigenetic abnormalities, are hallmarks of pancreatic tumors." (PMID 36558998, 2022). "More than 90% of pancreatic tumors harbor a KRAS mutation, which is considered an early driver mutation essential in the initiation of pancreatic carcinogenesis." (PMID 35785187, 2022). "For that study, we selected the breast cancer MDA-MB-231 xenograft model that contains KRAS mutation, which is also present in 80–95% of pancreatic cancer specimen from patients." (PMID 35326668, 2022). "The process of autophagy is highly active in pancreatic cancer cells and autophagy is upregulated in KRAS mutated cells." (PMID 35785187, 2022). "Pancreatic ductal adenocarcinoma (PDAC) comprises approximately 90% of pancreatic cancer cases, with the majority of those patients carrying active KRAS mutations." (PMID 36123703, 2022). "The biodegradable polymer matrix, Local Drug EluteR (LODER), was used to release the G12D-mutated KRAS-targeted siRNA locally within a pancreatic tumor microenvironment for controlled and prolonged delivery." (PMID 35890348, 2022). "Here, we found that SEMA3C was highly expressed in pancreatic cancer and associated with the KRAS G12D mutation." (PMID 35785187, 2022). "The KRAS G12C mutation is also found in a small fraction of pancreatic cancers, and sotorasib showed efficacy in pancreatic cancer in a phase 1 study." (PMID 35328306, 2022). "More than 90% of pancreatic cancer patients have KRAS carcinogenic point mutations, which constitutively activate the RAS signaling pathway." (PMID 35193647, 2022). "Meanwhile, a large number of pancreatic cancer precursor cells named pancreatic intraepithelial neoplasia (PanIN) are gradually generated in the pancreas of mice carrying KRAS mutation." (PMID 35965507, 2022). "We observed that the AP1 family member FRA1 is tightly linked to the KRAS signal and expressed in pre-malignant lesions and the basal-like subtype of pancreatic cancer." (PMID 36534167, 2022). "Patients with KRAS mutated tumors were also significantly associated with a worse prognosis in overall survival of pancreatic cancer patients compared with KRAS WT tumors." (PMID 35785187, 2022). "The highest incidence of mutational activation occurs in lung, colorectal and pancreatic cancers, where KRAS mutations are associated with increased tumorigenicity and poor prognosis." (PMID 36011352, 2022). "Mutation of KRAS gene can alter the tumor microenvironment of pancreatic cancer by changing the composition of extracellular matrix after inducing the production of various chemokines and fibroblasts." (PMID 36118526, 2022). "There are several studies on the KRAS mutation related prognosis and multiple studies stated that poor outcomes were identified in patients with KRAS G12D mutant pancreatic cancer." (PMID 35785187, 2022). "Of note, the notion that KRAS mutations operate independently of upstream signaling has been challenged by genetic mouse models of lung and pancreatic cancers, which showed that EGFR inhibition prevented the growth of KRAS-mutated tumors." (PMID 36077604, 2022).
pancreatic cancer (continued). "Long noncoding RNA AC245041.2 was proved to be related to KRAS mutation and survival outcome of pancreatic cancer patients." (PMID 35198013, 2022). "High KRAS mutation ratio (≥5%) in circulating exosomal DNA is associated with shorter progression-free survival and overall survival of pancreatic cancer patients." (PMID 35159011, 2022). "The aim of our study was to evaluate the impact of the oncogenic KRAS G12D mutation on the activity of the error-prone alt-EJ repair mechanism, and to investigate the potential role of Polθ in the development of pancreatic cancer." (PMID 36077614, 2022). "In a phase I study, Afatinib, together with another agent selected from the CTRP database, Selumetinib, was administrated on KRAS-mutated pancreatic cancer." (PMID 36186449, 2022). "Mutant KRAS is the most prominent oncogene in human cancers, and in particular, pancreatic cancer carries the highest rate of mutation to KRAS and is one of the most lethal type of tumor." (PMID 35594991, 2022). "The KRAS mutation has been shown to promote hyperproliferation in colon cancer and pancreatic cancer; there are also reports of various mechanisms through which RAS activation can lead to replication stress and cellular senescence." (PMID 35243242, 2022). "It is worth noting that the KRAS G12D mutation, the most common mutant allele in pancreatic cancers, has been shown to preferentially activate the JNK pathway." (PMID 36232313, 2022). "This correlation further suggested that the KDM5 family plays a unique role in malignant tumors driven by KRAS mutations, including pancreatic cancer." (PMID 35493099, 2022). "Gene mutations also play a critical role in the progression and evolution of pancreatic cancer, especially KRAS mutations and other key mutations in pancreatic cancer." (PMID 36261830, 2022). "Various mechanisms of cell death related to apoptosis, KRAS mutation and cell cycle modulation have been described when extract or isolated biomolecules have been used in pancreatic tumor culture cells." (PMID 36362920, 2022). "The results obtained for the G12C-mutated MIA PaCa2 and the G12D-mutated pancreatic cancer cell lines are compared to the BxPC3 cell line that exhibits an unusual KRAS wildtype." (PMID 36048281, 2022). "Targeting mutated KRAS, the most renowned driver gene in pancreatic cancer, is an active area of study." (PMID 35785187, 2022). "Ninety-two percent of pancreatic cancers with KRAS mutations can promote the recruitment of MDSCs and Tregs through the secretion of cytokines such as granulocyte-macrophage colony-stimulating factor (GM-CSF)." (PMID 36499340, 2022). "Mutations in the KRAS oncogene are required for alcohol to promote pancreatic cancer in mice, but little is known about the molecular events associated with the combined exposure of alcohol and mutant KRAS expression in pancreas cells." (PMID 35454872, 2022). "A recent study showed that a therapeutic antibody targeting KRAS synergistically increased the antitumor activity of gemcitabine by inhibiting RAS downstream signaling in pancreatic cancer with KRAS mutation." (PMID 36127339, 2022). "In this study, we established PCOs and isolated CAFs from human pancreatic cancer tissues, and the KRAS G12D mutation was identified in pancreatic cancer tissues and all established organoid lines." (PMID 35565206, 2022). "Activating mutations in the KRAS gene are widespread in more than 90% of pancreatic cancers and are considered to be an essential cause of pancreatic carcinogenesis." (PMID 36358856, 2022). "The phosphorylation of selected kinases of MIA PaCa-2 and Aspc1 pancreatic cancer cell lines were compared to BH1362 NSCLC cell line carrying a KRAS G12C mutation for controls and cells pretreated with BAY-293 in Western Blot arrays." (PMID 36048281, 2022).
pancreatic cancer (continued). "There is still a lack of clear understanding of the prognostic value of different KRAS mutation subtypes in pancreatic cancer." (PMID 35785187, 2022). "KRAS mutations are the most common mutations in human solid tumors 6, and can be found in 90% of pancreatic cancer patients." (PMID 36118526, 2022). "First, we did not perform further molecular tests for CTC identification, such as KRAS mutation, which is the most common mutation in pancreatic cancer." (PMID 35740311, 2022). "The study indicates that SEMA3C is a potentially promising and attractive target for pancreatic cancer therapy especially in patients with a G12D mutation in KRAS." (PMID 35785187, 2022). "Considering the heterogeneity of mutation subtypes in KRAS, KRAS-mutant pancreatic cancer cell lines were grouped by their mutational status at codons 12 (G12V, G12D, G12R, and G12C)." (PMID 35806187, 2022). "The presence of KRAS mutations in the ctDNA of pancreatic cancer patients has been shown to be indicative of progression free and overall survival." (PMID 35448266, 2022). "In two pancreatic cancer cell lines bearing the KRAS G12D mutation (PANC-1 and Panc 04.03), TH-Z827 conferred anti-proliferative effects with IC50 values of 4.4 and 4.7 μM, respectively." (PMID 35075146, 2022). "The Hedgehog signaling is found to be phosphorylated in early pancreatic tumors, and the activation of this signaling is important during the cellular progression and is associated with the KRAS mutations." (PMID 36556296, 2022). "KRAS is the most frequently mutated oncogene in pancreatic cancer, and is mutated in more than 90% of all cases." (PMID 35897809, 2022). "Given the heterogeneity of these results, we sought to assess the correlation between the KRAS G12D mutation subtype and survival in pancreatic cancer patients across all clinical stages using tissue biopsies obtained predominantly via EUS-FNA." (PMID 36231137, 2022). "Given that KRAS is mutated in up to 90% of pancreatic cancers, mouse models with the same mutation have been used to study the role of RON." (PMID 35454943, 2022). "These genes are often found to be highly expressed in primary pancreatic tumors with the KRAS p.G12V mutation." (PMID 35897809, 2022). "The mutated oncogene KRAS, found in advanced pancreatic cancer, encodes a small GTPase that regulates the downstream signaling from growth factor receptors." (PMID 36556296, 2022). "A further experiment showed its effectiveness on KRAS-mutated pancreatic cancer in a mouse model, but significant side effects were also observed in this case." (PMID 35409064, 2022). "Mutations in KRAS are common in many solid tumors, most frequently occurring in 45% of colorectal, 35% of lung, and up to 90% of pancreatic cancers." (PMID 35573474, 2022). "In a given cancer type, KRAS mutations are the predominant RAS mutations found in pancreatic cancer (~ 88%)." (PMID 35045886, 2022). "One contribution of oncogenic KRAS mutations to the oncogenesis and progression of pancreatic cancer is oncogenic KRAS mutation-driven metabolic rewiring." (PMID 36408139, 2022). "In contrast, within the KRASnon-G12C cohort, pancreatic tumors had the highest KRAS mutation prevalence (30%), followed by CRC (23%) and TUO (18%)." (PMID 35319967, 2022). "A mutation of the oncogene Kirsten rat sarcoma (KRAS) is the most common cause of pancreatic cancer, accounting for more than 90% of cases." (PMID 35804932, 2022). "KRAS mutations occur in about 90% of pancreatic cancer and KRAS is a significant oncogene for the initiation of this cancer type." (PMID 35785187, 2022).
pancreatic cancer (continued). "KRAS mutated pancreatic cancer is characterized by high KRAS expression and the presence of a chirality-dependent tumour microenvironment." (PMID 36619305, 2022). "KRASG12D, the most common oncogenic KRAS mutation, is a promising target for the treatment of pancreatic cancer." (PMID 36618907, 2022). "Mutations in KRAS can impair T cell recognition of pancreatic cancer cells, leading to immune evasion." (PMID 36212154, 2022). "KRAS (Kirsten Ras protein) was found to be the most common locus for somatic gain-of-function mutations in patients with pancreatic cancer, accounting for about 95%." (PMID 36618907, 2022). "Then we combined KRAS G12D associated DEGs with the genes that are highly expressed in pancreatic cancer patients in other 3 cohorts (TCGA/GSE62125/GSE71989)." (PMID 35785187, 2022). "Our previous research and recent local and foreign reports confirmed that the ITGA2 overexpression in pancreatic cancer is caused by the mutation and abnormal activation of KRAS." (PMID 35193647, 2022). "SEMA3C can be used as a novel target or marker with therapeutic or diagnostic potential in pancreatic cancer especially in tumors harboring the specific KRAS G12D mutation." (PMID 35785187, 2022). "One of the unique genomic features of pancreatic cancer is that >90% of the tumors harbor KRAS mutations." (PMID 36232820, 2022). "It is noteworthy that other different solid tumors can have a KRAS mutation, notably a KRAS G12C mutation, such as some colon and pancreatic carcinomas." (PMID 35406400, 2022). "In this regard, a recent clinical trial [CodeBreaK100 (NCT03600883)] demonstrated the efficacy of the sotorasib in pancreatic carcinoma mutated for KRAS G12C." (PMID 35406400, 2022). "CD47 functionalized exosomes loaded with anti-KRAS G12D are promising delivery platforms to silence KRAS G12D expression and reduce pancreatic tumor burden exclusively in G12D-mutated KRAS-harbored cancerous pancreatic cells." (PMID 34371702, 2021). "We then performed cell viability assay for AMG510, and MRTX849 in different cancer types (NSCLC, CRC, and pancreatic cancer) including KRAS wild type, KRAS non‐G12C mutation, and KRAS G12C mutation cell lines." (PMID 34151545, 2021). "Third, given that the KRAS oncogene is among the most frequently mutated genes in pancreatic cancer, a study on the metabolism of pancreatic cancer cells indicated that they rely on a distinctive pathway." (PMID 34680237, 2021). "Almost 95% of cases of PC have point mutation at G12, G13, and Q61 codons in the KRAS activation domain as a result of the mutant Kras protein generation, which provokes growth and proliferation of pancreatic tumors." (PMID 34575504, 2021). "As already mentioned, RAS gene proteins are often mutated in human cancers: NRAS is most frequently mutated in melanoma, KRAS mutations are prevalent in lung, colorectal and pancreatic cancers, while HRAS mutations are reported in a minority of cases." (PMID 34944952, 2021). "The KRAS gene is the most frequently mutated oncogene in human cancers, particularly in tumors of the pancreas, colon and lung, and has consequently been a major focus of cancer drug discovery for decades." (PMID 34257283, 2021). "In total, 70 patients who underwent surgery for pancreatic cancer were included in the study to determine the presence of KRAS mutations in tissues and blood." (PMID 34829828, 2021).
pancreatic cancer (continued). "We found that pancreatic cancer cell lines, 85% of which present with KRAS mutations, were significantly more dependent on KRAS than were all other cell lines (t = 35.4, p = 2.8 × 10−178)." (PMID 33398072, 2021). "For example, in this study, ZNF154 methylation outperformed KRAS mutations in pancreatic cancer, when counts of any methylated ZNF154 fragment were used to classify cancer versus control plasma samples." (PMID 33420235, 2021). "As the disease progresses, mutations in KRAS accumulate and is thus observed in > 90% of pancreatic cancer cases." (PMID 38107772, 2021). "Over 90% of pancreatic cancers are known to harbor activating KRAS mutations and the other 10% have oncogenic fusions, BRAF mutations, Receptor Tyrosine Kinase (RTK) mutations/amplifications, or AKT/mTOR activation." (PMID 34504655, 2021). "Single guide RNAs (sgRNAs) were designed to target the Cas9 nuclease to KRAS exons 4A or 4B in the human lung and pancreatic cancer cell lines A549 (G12S mutation) and SUIT2 (G12D mutation)." (PMID 34257283, 2021). "Mutated KRAS in pancreatic cancer plays a central role in tumor development and growth by regulating T-cell cytokines in TME." (PMID 34616403, 2021). "Metabolic reprogramming and mitochondrial dysfunction have been reported in pancreatic cancer, and by enhancing the nucleotide biosynthesis, the frequently mutated KRAS gene stimulates cancer cell proliferation." (PMID 34073722, 2021). "Preclinical data consistently indicate that inhibition of the RAS-RAF-MEK-ERK pathway results in an increased autophagy dependence in cancers driven by KRAS or BRAF mutations (90% of pancreatic cancer)." (PMID 34439102, 2021). "We used a panel of pancreatic tumour cell lines generated by KRAS mutation combined with other genetic alterations including PIK3CA mutation and PTEN deletion (Dataset EV4A)." (PMID 34033220, 2021). "In fact, a method to detect pancreatic cancer by assessing five DNA methylation markers in cfDNA along with KRAS mutation status had 68% sensitivity and 86% specificity when tested on cfDNA samples from 47 pancreatic cancer patients and 14 normal volunteers." (PMID 34439749, 2021). "IPMN with associated invasive carcinoma and pancreatic cancer have an overlapping yet distinct genetic mutation, such as KRAS and GNAS." (PMID 34178672, 2021). "KRAS mediates downstream signaling of growth factor receptors, and its mutational activation drives over 90% of pancreatic cancers." (PMID 35127473, 2021). "In this study, we found upregulation of TFCP2 expression in pancreatic cancer was associated with KRAS mutation." (PMID 34804919, 2021). "In pancreatic cancer mutations in the oncogene KRAS are essential for tumorigenesis and impact directly multiple metabolic pathways of PDAC." (PMID 33632214, 2021). "For example, case #44 in our study involved liver metastasis from a mutation in the KRAS p.G12V gene, which is a common mutation in pancreatic tumors." (PMID 34692498, 2021).